FAP (fibroblast activation protein alpha)
Diseases named in the same sentence as FAP in open-access papers (continued):
Sharing a sentence is not in itself a finding about the gene and the disease.
tumor (continued). "FAP expression was also seen in a portion of the normal tumor-adjacent samples examined, though at lower levels than in the tumor samples, which has been reported previously." (PMID 37333052, 2023). "Co-injection of [68Ga]Ga-AV02053 and [68Ga]Ga-AV02070 with FAPI-04 (250 μg) reduced the uptake of [68Ga]Ga-AV02053 and [68Ga]Ga-AV02070 in HEK293T:hFAP tumor xenografts to almost background level, confirming the uptake of both tracers is FAP mediated." (PMID 36986548, 2023). "Results from these studies suggest that FAP-α participates in “tumor-stroma cross-talk”, with the tumor microenvironment playing an important role in FAP-α promoting tumor growth." (PMID 36937451, 2023). "Further work to characterize FAP expression in normal tissue is needed to understand the potential for on-target off-tumor effects with FAP-targeted interventions." (PMID 37333052, 2023). "The immunosuppressive effects of FAP + CAFs in multiple malignancies have also been described, with their depletion enabling effective tumor progression control." (PMID 37723510, 2023). "FAP holds the promise to be a pan-cancer target, owing to its selective over-expression in a vast majority of neoplasms, particularly epithelial cancers." (PMID 37370912, 2023). "The intensity of FAP, articulated by both “Intensity %” and “Intensity score”, is lower in the first metastasis compared to the primary tumor with a statistically significant correlation." (PMID 37892020, 2023). "The majority of tumor samples had FAP IHC intensity scores ≥2 and density scores ≥25% for stromal cells (77.7%) and tumor cells (50.7%)." (PMID 37333052, 2023). "It was discovered that FAP was robustly expressed not only on immunosuppressive tumor stromal fibroblasts but also on multipotent bone marrow stromal cells (BMSCs) in mice and humans." (PMID 38516299, 2023). "Immune profiling of harvested tumors revealed robust tumor infiltration and accumulation of FAP(hF1) UCAR T-cells, as measured by quantity of detected human CD45+ cells." (PMID 37251405, 2023). "This can be accomplished by the use of less lipophilic linkers such as PEG linkers and well as piperazine-based linkers which have been shown to be important for maintaining good tumor uptake of FAP-targeting tracers." (PMID 36770755, 2023). "Quantitative analysis using Qupath software showed that FAP protein levels were significantly enhanced at PanCK(−) areas of tumor invasive margin compared to tumor center and adjacent normal areas." (PMID 37964075, 2023). "Previous evidence has already demonstrated a significant role of FAP in tumor progression through multiple mechanisms." (PMID 37325617, 2023). "It is now understood that cancer-associated fibroblasts (CAFs), which express specific fibroblast activation protein (FAP), are critical participants in tumor development and metastasis." (PMID 36831535, 2023). "Collectively, minimal sustained toxicity was observed in the tumor-bearing mice treated with FAP-CAR T cells compared to controls." (PMID 37607999, 2023). "Radiopharmaceuticals targeting the fibroblast activation protein alpha (FAP) can be used in many different cancer types since FAP is highly expressed in the tumor microenvironment of almost all epithelial cancers." (PMID 36980775, 2023). "In order to confirm the binding specificity to FAP, [68Ga]Ga-DOTA-FD1 and excess unlabeled FD1 (750 μg) were co-injected into HT1080-FAP tumor models, in which the cold FD1 competitively bound to and saturated the target." (PMID 38706713, 2023). "The visually estimated mean percentage of FAP-labeled tumor cells was 51.1% ± 36.2% for canine, 56.6% ± 21.3% for feline, and 61.1% ± 41.7% for human STS." (PMID 37727209, 2023). "Next, we compared the grade of infiltration for each fibroblast subtype in distinct tissues and observed that FAP + fibroblasts mainly existed in tumor regions, including the cancer core and border." (PMID 37344903, 2023).
tumor (continued). "Silencing FAP has been shown to induce tumor cell apoptosis, indicating its important role in cancer cells survival." (PMID 36986548, 2023). "In the present study, it was observed that serum FAP exhibited a progressive elevation in conjunction with the augmentation of tumor volume." (PMID 37864148, 2023). "This demonstrates that a pyridine-based FAP-targeted tracer has the potential to achieve good tumor uptake, a low background, and improved tumor-to-background contrast." (PMID 36986548, 2023). "OMTX705 is a first-in-class antibody–drug conjugate (ADC) that targets the tumor microenvironment with FAP-dependent cytotoxic activity." (PMID 37007004, 2023). "In pancreatic cancer, depleting the CAF FAP+ population slowed tumor growth and increased CD8+ T-cells tumor infiltration." (PMID 37185432, 2023). "IHC/mIHC staining also showed that FAP-positive fibroblasts (mCAFs) were located near the tumor nest edge and in close contact with p-EMT cells there, prompting consideration of the interaction between mCAF and mEpCs, such as ligand-receptor signaling." (PMID 37853464, 2023). "To summarize, the results indicated that PI3K/Akt and WNT signaling pathways were significantly upregulated at the EOCC tumor invasive margin in PanCK(+) tumor epithelial cells and FAP(+) CAFs, respectively." (PMID 37964075, 2023). "Future optimization by the addition of albumin binding moieties, in order to increase its blood residence time and maximize tumor uptake, is warranted, especially for the design of radiotherapeutic agents to treat FAP-expressing tumors." (PMID 37110717, 2023). "FAP+ fibroblasts have also been identified in PDAC as tumor-promoting CAFs, performing possibly through stromal-derived factor 1 (SDF-1) and C-C motif chemokine ligand 2 (CCL2) dependent manner." (PMID 36793444, 2023). "CAFs with FAP expression are found in various neoplasms, particularly epithelial cancers, and malignancies with a strong desmoplastic reaction such as breast, colorectal, pancreatic, and lung cancer." (PMID 37370912, 2023). "It is even more important taking into consideration that CAF populations of different tumor-promoting abilities and phenotype (CD49e+, fibroblast activation protein FAP-high or FAP-low) have been identified." (PMID 37448521, 2023). "The study observed an increase in serum FAP levels as tumor progression, while a decrease in these levels was observed following chemotherapy." (PMID 37864148, 2023). "In this study we have demonstrated that human NK cells express FAP and that FAP directly affects NK cell migration, extravasation and tumor infiltration." (PMID 38196606, 2023). "The objective of this study was to investigate FAP expression of CAF in the tumor microenvironment of CRC and to evaluate FAP as a candidate for targeted imaging and therapy." (PMID 37614665, 2023). "FAP expression promotes tumor growth and invasion, emerging as an excellent candidate for diagnostic and therapeutic applications alongside modulation of the TME." (PMID 38102692, 2023). "Studies have reported that the FAP inhibitor talabostat significantly inhibits tumor growth in patients with early-stage COAD but shows limited efficacy in patients with advanced-stage COAD." (PMID 37490719, 2023). "Cancer-associated fibroblasts differ from normal fibroblasts by providing FAP as a target with a relatively high tumor-specific expression." (PMID 36832085, 2023). "This study assesses the predictive role of FAP expression in determining the response to immunotherapy among tumor patients treated with ICIs." (PMID 37490719, 2023). "In recent years, the depletion of FAP in CAFs by multiple methods, including cell‐based vaccines has been reported to induce the immune system and inhibit tumor progression." (PMID 37773704, 2023). "High expression of FAP in these cancers was reported to estimate worse outcomes in patients and involved in tumor progression via diverse mechanisms." (PMID 37325617, 2023).
tumor (continued). "The degree of FAP staining observed in the primary tumor parenchyma was found to be directly proportional to the concentration of serum FAP in these individuals." (PMID 37864148, 2023). "QUESTION: Will a heterodimer that recognizes both FAP and integrin αvβ3 yield improved tumor uptake compared with 18F-FDG or 68Ga-FAPI-46?" (PMID 37142301, 2023). "The prodrug uses the enzymatic action of FAP to kill FAP+ cells, a mechanism more often used in tumor therapy to help the drug unlock its target more precisely and avoid damage to normal tissue from non-specific cytotoxic drugs." (PMID 37006278, 2023). "The cancer supportive functions of the tumor stroma and FAP expression by CAFs have stimulated the investigation of approaches to therapeutically target FAP in various cancer types." (PMID 37333052, 2023). "The presence of FAP-expressingfibroblasts throughout the whole tumor as shown with IHC suggeststhat 28H1-700DX indeed binds to FAP, while the uptake of DP47GS-700DXmight be partly FAP-independent." (PMID 37485886, 2023). "The higher FAP expression in CCC was also demonstrated in immunohistochemical staining of the tumour tissues." (PMID 37608378, 2023). "In conclusion, BC-PDMs largely reflect the hormone receptor status of the corresponding tumor tissue and exhibit heterogeneous expression of CKs and FAPα, which are markedly different in HR+ and TNBC and ILC/NST BC-PDMs." (PMID 37596623, 2023). "To evaluate anti-tumor efficacy, we administered 5 × 106 FAP-CAR+, Meso-CAR+ and a comparable number of total MigR control T cells or PBS intravenously in mice when tumors reached a mean volume of 100–150 mm3." (PMID 37607999, 2023). "In comparison, T3M-4 tumor cells are surrounded by stroma cells that naturally express FAP at a high level." (PMID 38706713, 2023). "Both mRNA and miR approaches confirmed previous knowledge about the impact of CXCR4 and FAP on tumor microenvironment." (PMID 36672341, 2023). "In a similar manner, FAP-CAR T cells enhanced access of Meso-CAR T cells to tumor nests when given in combination." (PMID 37607999, 2023). "The findings revealed a positive correlation between the level of FAP and tumor volume as observed on MR images." (PMID 37864148, 2023). "Fibroblast activation protein-α (FAP) is a transmembrane serine protease and is highly expressed on CAFs in most types of tumor tissues." (PMID 36851271, 2023). "We then explored the impact of genetic manipulation and pharmacologic inhibition of FAP on NK cell migratory properties, extravasation, and tumor infiltration." (PMID 38196606, 2023). "Further investigations are warranted to identify novel strategies targeting FAP to overcome tumor stromal barriers and broaden the clinical effectiveness of immunotherapy." (PMID 37166418, 2023). "FAP-targeted CAR-T cells were also developed to control tumor growth by activating the function of endogenous immune cells." (PMID 37046312, 2023). "Using genetically engineered T cells that express FAP-specific CARs, we can instigate an anti-tumor response that diminishes stromal cells and suppresses tumor growth." (PMID 37760801, 2023). "One example of a target is the fibroblast activation protein (FAP), which is overexpressed in activated fibroblasts of the tumour microenvironment, where it plays a key role in ECM remodelling and regulates CAF proliferation and migration." (PMID 36980527, 2023). "Tumor epithelial cells at tumor invasive margin of EOCC tumors neighboring FAP(+) CAFs show significantly higher mRNA/protein levels of fibroblast growth factor receptor (FGFR2) and PI3K/Akt signaling activation." (PMID 37964075, 2023). "This study elucidates the role of FAP in tumor development and provides a valuable reference for targeting FAP to enhance immunotherapy." (PMID 37490719, 2023).
tumor (continued). "The LuMIERE study a prospective phase I/II study in patients with advanced or metastatic solid tumors evaluating the safety, dosimetry, pharmacokinetics, and preliminary anti-tumor activity of [177Lu]Lu-FAP-2286." (PMID 36813980, 2023). "FAPI PET/CT is a novel imaging tool targeting fibroblast activation protein (FAP), with high tumor uptake rate and low background noise." (PMID 36675506, 2023). "The biodistribution data of mice co-injected with natGa-FAPI-04 (0.5 mg/mouse) revealed a ~96% reduction in the tumor uptake and further substantiated the in vivo FAP specificity of our lead candidate [68Ga]Ga-SB03045." (PMID 37110717, 2023). "The blocking studies of [18F]21 with FAPI-04 showed a significant reduction in tumor uptake (14.13 ± 3.19%ID/g vs. 3.8 ± 0.89%ID/g), validating the FAP specificity of [18F]21 in vivo." (PMID 36864362, 2023). "The results showed that tumor invasiveness can be effectively inhibited by inhibiting FAP expression, and PT100 exerted an exciting effect on inhibiting the invasion of tumor cells." (PMID 36382346, 2023). "In this study, the Tumor IMmune Estimation Resource (TIMER) was used to predict the correlation between FAP expression and M2‐type macrophage numbers in LGG and GBM." (PMID 36382346, 2023). "Along the expression of FAP, macrophage frequency and expression of genes related to MDSCs have been shown to increase significantly, leading to tumor infiltration of MDSCs and T cells." (PMID 38313431, 2023). "Of notice, FGFR2 was also detected as upregulated in FAP(+) stromal cells at the tumor invasive margin of EOCC." (PMID 37964075, 2023). "DNA vaccine: The use of DNA vaccine encoding FAP successfully induced CD8 T-cell mediated killing and significantly suppressed tumor growth in both breast and colon murine models." (PMID 37035187, 2023). "The tumor-targeting efficiency, biodistribution and optimal imaging time window of the [68Ga]Ga-FAP-2286-ICG were studied in mice bearing U87MG xenografts." (PMID 38026901, 2023). "The results showed that 177Lu-FAP-2286 led to higher tumor retention and showed better tumor control than 177Lu-FAP-46." (PMID 37835533, 2023). "After treatment with conventional therapies, CAFs strongly expressed FAP, suggesting that FAP-targeted NIR-PIT has the potential to selectively delete local CAFs in the tumor." (PMID 37296933, 2023). "This was accompanied by reduced desmoplasia in FAP(hF1) UCAR T-cells treated tumor stroma, as measured by collagen depletion." (PMID 37251405, 2023). "Recent years have witnessed a growth in research on FAP-targeted molecular agents for tumor diagnosis and therapy." (PMID 38706713, 2023). "These tumor-infiltrating FAP-CAR T cells exhibited relatively high levels of mean track speed and track length." (PMID 37607999, 2023). "Our study highlights the significant FAP increase in CRC supporting its role as a promising target in tumor biology." (PMID 37892020, 2023). "A peptide that targets FAPα can selectively deliver drugs or imaging agents to CAFs and inhibit their tumor-promoting functions." (PMID 37601380, 2023). "In vitro studies of competitive binding to FAP, cellular internalization, and efflux characteristics were determined using FAP-positive A549-FAP cells and a murine tumor model." (PMID 36813980, 2023). "FAP-positive CAFs are the major source of C–C motif chemokine ligand 2 (CCL2) which can promote tumor growth by enhancing the recruitment of myeloid-derived suppressor cells." (PMID 37316886, 2023). "In FAP(+) CAFs of EOCC tumor samples, the GSEA pathway analysis showed the upregulation of WNT signaling, VEGA-VEGFR2 pathway, and Notch signaling." (PMID 37964075, 2023). "FAPI-04 turned out to be the most promising because of good stability in human serum, high affinity for FAP, and high tumor uptake." (PMID 36835275, 2023). "FAP transfected cell-line MCF-7-FAP was employed in cellular experiments because of the limited expression of FAPI in tumor cells." (PMID 36879039, 2023).
tumor (continued). "Next, we investigated the genomic alteration feature of FAP in different tumor samples of TCGA datasets." (PMID 37166418, 2023). "To investigate the correlation between the expression of FAP and prognostic indicators in tumor patients, namely OS, DFI, PFI, and DSS, we employed a Cox regression model and conducted KM survival analysis for each type of cancer." (PMID 37490719, 2023). "Lin28b can be expressed in a variety of CAFs including aSMA+ myofibroblasts and FAP+ myofibroblasts which support tumor growth." (PMID 37898598, 2023). "In our study, 62.3% of canine (33/53), 87.5% of feline (21/24), and 69.2% of human STS (27/39) show an intermediate-to-high FAP expression score with 31%, 33%, and 42% of the tumor area being positive for FAP, respectively." (PMID 37727209, 2023). "Potential ligand-receptor interaction analysis showed that FGF20 ligand produced in FAP(+) CAFs at EOCC tumor invasive margin had the highest interaction potential to bind to FGFR2 in PanCK(+) tumor epithelial cells at EOCC tumor invasive margin." (PMID 37964075, 2023). "U87MG tumor-bearing mice were imaged at several time points (0.5, 1, 2, 24, 48, and 72 h) after FAP-2286-ICG injection to determine the optimal time for FI." (PMID 38026901, 2023). "We then analyzed the correlation between COL10A1/FAP/FN1 and tumor immune cells, and the outcomes showed that FAP had significant positive correlations with macrophages, Th1 cells, neutrophils, iDC, Tgd, TReg, mast cells, and NK cells (R > 0.4, P < 0.001)." (PMID 38063927, 2023). "Fibroblast activation proteins (FAP) are overexpressed in the tumor stroma and have received attention as target molecules for radionuclide therapy." (PMID 37240044, 2023). "In 7 of 9 patients, we found a large amount of CAFs around tumor cells, with moderate or high FAP staining." (PMID 37046312, 2023). "At the same time, because of the low expression of FAP in normal tissues, the strategy of targeting FAP has obvious advantages in tumor treatment, which is worth further study." (PMID 36675506, 2023). "Fluorescent probes and 68Ga-FAPi-46 PET have been used to identify FAP CAF subpopulations that modulate tumor aggressiveness." (PMID 37046676, 2023). "The resistance to ICIs is in part mediated by immune-suppressive cells in the tumor microenvironment (TME), such as fibroblast activation protein (FAP)-expressing cancer-associated fibroblasts (CAFs)." (PMID 37086273, 2023). "This suggested that the optimal surgical operation time should be performed within the time frame of massive tumor accumulation and clear profile after injection of FAP-2286-ICG." (PMID 38026901, 2023). "Another approach for tumor treatment involves the activation of combinations called “prodrugs” by FAP." (PMID 37006278, 2023). "The higher FAP expression was correlated with larger tumor size (p = 0.002), higher stage of ypN (p = 0.034), poorer degree of differentiation (p = .031), and a greater tendency to lymphovascular invasion (p = 0.016), and nerve invasion (p = 0.029)." (PMID 37277751, 2023). "Using cell fractions mode, cell proportions of EPCAM(+) tumor epithelial cells, FAP(+) CAFs, CD45(+) leucocytes, and CD31(+) endothelial cells were generated for each tissue sample." (PMID 37964075, 2023). "In summary, FAP is primarily expressed in fibroblasts of gastrointestinal cancers and promoted cancer progression via promoting tumor cell motility as well as macrophages infiltration and M2 polarization." (PMID 37325617, 2023). "The FAP and CTGF genes are most active in activated fibroblasts including myofibroblasts and tumor-associated fibroblasts." (PMID 37108352, 2023). "FAP+ CAFs can protect tumor cells from tumor necrosis factor and interferon-mediated T-cell necrosis and can express CXC motif chemokine ligands, inhibiting T-cells from accessing tumor cells." (PMID 36793444, 2023).